NLRP3 (NLR family pyrin domain containing 3)
Diseases named in the same sentence as NLRP3 in open-access papers (continued):
Sharing a sentence is not in itself a finding about the gene and the disease.
silicosis (continued). "Therapeutic strategies targeting the NLRP3 inflammasome, either through direct inhibitors or by modulating its upstream activators, may hold promise for preventing or treating silicosis." (PMID 40119408, 2025). "A limited number of studies have implicated a role for the NLRP3 inflammasome in silicosis, however, the distribution of NLRP3 expression and its activation in the lung are currently not well characterized." (PMID 40119408, 2025). "Targeting multiple pathways, including the NLRP3 inflammasome, as a therapeutic approach may be critical to suppress the overstimulation of inflammatory pathways in silicosis." (PMID 40119408, 2025). "Together, these findings indicate that the NLRP3 inflammasome plays a central regulatory role in silicosis, and further suggest that activated NLRP3 may serve as an important biomarker of silicosis." (PMID 38515835, 2024). "Moreover, both the NLRP3 activation and silicosis development were influenced by modulation of the surface properties of the silica particles." (PMID 36669831, 2023). "Given the sound inhibitory effects of Tet against IL-1β, it is reasonable to speculate that the effectiveness of Tet treatment against silicosis is likely mediated by suppressing activation of the NLRP3 inflammasome." (PMID 34417574, 2022). "We therefore hypothesized that the therapeutic anti-silicosis effects of Tet may be meditated by inhibiting the activation of NLRP3 inflammasome." (PMID 34417574, 2022). "In addition, based on multiple transcriptomics approaches, we provide the first report of Tet-mediated alleviation of silicosis via inhibition of NLRP3 inflammasome pathway signaling." (PMID 34417574, 2022). "Furthermore, our work also provides strong evidence for clinical strategies that combine Tet with NLRP3 inflammasome pathway inhibitors to increase the efficacy and therapeutic range available for silicosis patients." (PMID 34417574, 2022). "Hence, we proposed that suppression of NLRP3 inflammasomes contributed to the anti-silicosis effects of Tet that mainly occurred in macrophages." (PMID 34417574, 2022). "Furthermore, because silicosis is mediated in part by the NLRP3 inflammasome, these findings are consistent with the involvement of cathepsin Z in the activation of the NLRP3 inflammasome." (PMID 34864055, 2022). "In addition, using a murine silicosis model, we show that the RAB20 knockout greatly promoted a crystalline silica-induced silicosis-like picture through enhancing the NLRP3 inflammasome activity and IL-1β release." (PMID 36131930, 2022). "In silicosis there is a clear link between NLRP3 and the development of the disease." (PMID 34220810, 2021). "The NLRP3 inflammasome is activated in a one-step fashion, leading to downstream occurring events that are important in relaying the danger signal to the microenvironment contributing to the pathological condition of silicosis." (PMID 23402370, 2013). "The NLRP3 (NLR family pyrin domain-containing 3) inflammasome has been established as a major proinflammatory receptor for sensing environmental danger, such as crystalline silica, and subsequently initiating proinflammatory events during the progression of silicosis." (PMID 34417574, 2022). "In light of previous findings that Tet showed high affinity binding to alveolar macrophages and strongly inhibited production of IL-1β in macrophages, we thus speculated that the attenuation of silicosis by Tet might be ascribed to upstream blockade or inhibition of IL-1β and/or NLRP3 inflammasome." (PMID 34417574, 2022). "In addition, the NLRP3 inflammasome is essential for the development of silicosis." (PMID 23110140, 2012). "Bigelovin treatment significantly alleviates the severity of NLRP3‐related pulmonary disorders in murine models, such as LPS‐induced ARDS and silicosis." (PMID 40349158, 2025).
silicosis (continued). "Several candidate biomarkers for silicosis have been identified, namely, the interleukins, TGF-β, TNF-α, GF, chemokines, inflammatory proteins, NLRP3, and DNA methylation." (PMID 38515835, 2024). "Silica-stimulated macrophages activate pattern recognition receptors (PRRs) and NLRP3 inflammasome and release IL-1β, TNF-α, and interferons, which are the key mediators of silicosis pathogenesis." (PMID 36341426, 2022). "The activation of Caspase-3 and Caspase-6 is not dependent on Nlrp3, suggesting there are other singalings to activate silicosis induced cell death beside Nlrp3." (PMID 36459518, 2022). "Pulmonary inflammation in the context of silicosis is also maintained by non-immune cells and silica exposure leads also to upregulation of NLRP3 inflammasome-caspase-1 activation in lung epithelium." (PMID 35130879, 2022). "Specifically, we found that tetrandrine attenuated silicosis by inhibiting both the canonical and non-canonical NLRP3 inflammasome pathways in lung macrophages." (PMID 34417574, 2022). "In addition, deposition of macrophage receptors with collagenous structures (MARCO), NLRP3, caspase-1, ASC, IL-1β, and IL-18 was found in both glomerular and tubulointerstitial areas of patients with a history of silicosis." (PMID 33534121, 2021). "Interestingly, the integration of TLR-4/NLRP3/TGF-β signaling and metabolomics verified the importance of macrophage polarization in the silicosis fibrosis process." (PMID 34336106, 2021). "Recent studies demonstrated the NALP3 inflammasome is a protein complex (composed of NLRP3, ASC and caspase‐1) that is essential for the inflammatory response and the development of silicosis from silica exposure." (PMID 27917503, 2017). "However, NLRP3-dependent responses in the lung are not currently well characterized in the context of silicosis, and further work is required to mechanistically establish the significance of NLRP3 in the pathogenesis of silicosis." (PMID 40119408, 2025). "Of note, NLRP3 was observed in epithelial cells lining the alveoli, suggesting that its expression is not leukocyte-specific and suggests that epithelial NLRP3 may play a role in driving silicosis pathology." (PMID 40119408, 2025). "Given the observation that the absence of cathepsin Z does not completely prevent inflammation from occurring in our silicosis model, it is possible that there are NLRP3-independent processes contributing to the development of silicosis, as has previously been reported." (PMID 34864055, 2022). "To investigate the lysosome injury-mediated activation mechanism of NLRP3 in silicosis, we analyzed single-cell RNA sequencing analysis of cells from bronchoalveolar lavage fluid (BALF) obtained from small-scale mine workers with or without silicosis." (PMID 36131930, 2022).
brain injury (54 papers, 2014 to 2025). Acute and chronic (see also brain INJURIES, CHRONIC) injuries to the brain, including the cerebral hemispheres, CEREBELLUM, and brain STEM. "To elucidate the mechanism by which CPCGI mitigates microglial pyroptosis following brain trauma, we assessed the expression of key inflammasome‐related proteins, including NLRP3, pro‐caspase‐1, p20 caspase‐1, and GSDMD, using western blot analysis." (PMID 40059065, 2025). "Numerous studies have shown that the activation of the NLRP3 inflammasome is a major inflammatory response following spinal cord injury and traumatic brain injury." (PMID 40429643, 2025). "It showed that NLRP3 inflammasome participated in microglial polarization in a variety of brain injuries." (PMID 36875102, 2023). "HIF-1α also promotes NLRP3-driven microglial pyroptosis in the brain of mice with traumatic brain injuries, illustrating the tissue-independent pro-inflammatory crosstalk that exists between NLRP3 and HIF." (PMID 37375100, 2023). "Microglial A2AR or NLRP3 conditional knockout mice were used to interrogate the effects of this regulation on neuroinflammation posttraumatic brain injury (TBI)." (PMID 37564004, 2023). "P2X4 inhibition was also found to reduce microglial directed inflammation and apoptosis via Nod-like receptor protein 3 (NLRP3) inflammasome in rat brain trauma model." (PMID 36969557, 2023). "Early activation of the NLRP-3 inflammasome has been previously shown in a model of traumatic brain injury, where the authors described the neuroprotective effect of TH by dysregulating the inflammasome activation." (PMID 36835009, 2023). "Another study demonstrated that PI3K/AKT signalling inhibited the NLRP3 inflammasome via Nrf2 activation in a model of hypoxic-ischaemic brain injury." (PMID 37932279, 2023). "Activation of NLRP3 Inflammasome and Caspase-1 Activation: Under certain pathological conditions such as NDs and brain injuries, microglia can activate the NLRP3 inflammasome." (PMID 38020781, 2023). "The present study reports the importance of NLRP3, the canonical sensor of sterile injury, in the microglia and astrocyte responses during the acute phase of brain trauma." (PMID 35893807, 2022). "Previous publications from our laboratory demonstrated a high expression of proinflammatory cytokines and the NLRP-3 inflammasome only at the 24 h time point after the insult in our LPS presensitized model of HI brain injury." (PMID 35281473, 2022). "Studies proved that interference with NLRP3 inflammasome activation and IL-1β secretion effectively ameliorated the brain injuries." (PMID 35077922, 2022). "Here, we aimed to contribute to the understanding of the role of NLRP3 in microglial–astrocyte crosstalk in brain trauma by using both genetic and pharmacological approaches to inhibit NLRP3." (PMID 35893807, 2022). "NLRP3 inhibitors clearly have unique anti-inflammatory effects, protecting the injured brain after traumatic brain injury." (PMID 35222806, 2022). "The active NLRP3 inflammasome cleaves proinflammatory IL-1β to its active form, which is a key determinant of outcome after brain injuries." (PMID 34489645, 2021). "This current study aims to investigate the role of NLRP3 in repetitive mild traumatic brain injury (rmTBI) and identify the potential neuroprotective effect of saffron extract in regulating the NLRP3 inflammasome." (PMID 34506597, 2021). "We found an upregulation of NLRP3 gene expression following inflammation-sensitized HI brain injury, suggesting an involvement of the NLRP3 inflammasome as one potential regulatory pathway in LPS-sensitized HI brain injury." (PMID 33123073, 2020). "On a related note, Thakkar and colleagues recently found that activation of the NLRP3 inflammasome following ischemic brain injury was significantly impaired by estradiol signaling." (PMID 32252777, 2020). "Two recent studies have shown that melatonin inhibits NLRP3 inflammasome activation and oxidative stress in experimental acute brain injury." (PMID 31327964, 2019).
brain injury (continued). "Increased NLRP3 and cleaved caspase-1 and IL-1β levels were found in mouse models of traumatic brain injuries suggesting an important role for NLRP3 inflammasome." (PMID 31892810, 2019). "The NLRP3 inflammasome is a key effector protein in myeloid cells such as neutrophils and monocytes that amplifies inflammatory responses and ischemic brain injury by facilitation of caspase-1 and interleukin (IL)−1 β processing." (PMID 31787973, 2019). "The immunofluorescence and Western blotting detections showed that the induction of TBI increased the expressions of NLRP3 and caspase-1 in hippocampus tissues, indicating that the activity of inflammasomes was increased by brain injuries." (PMID 30232232, 2018). "Based on these results, we hypothesized that CPCGI regulates NLRP3 inflammasome‐mediated pyroptosis in microglia, thereby establishing a more favorable local microenvironment that mitigates neuronal injury following brain trauma." (PMID 40059065, 2025). "These preliminary data showed a possible role of the NLRP-3 inflammasome, not only in regulating the inflammatory response of microglial cells, but also from neutrophils during the inflammatory resolution after HI brain injury." (PMID 36835009, 2023). "Our results indicate an important role for NLRP3 inflammasome activation after brain trauma." (PMID 35893807, 2022). "Clemastine, as an antihistamine, has a positive anti-neuroinflammatory effect, could reduce the activation of microglia and down-regulate the expression of IL-1β and NLRP3 in rats with hypoxic-ischemic brain injury." (PMID 34497527, 2021). "Notably, HFD in the presence of TBI showed significant diet*injury interactions with exacerbation of HFD-dependent increases in VAT pro-inflammatory molecules IL-1β and NLRP3, indicating a brain trauma-dependent amplification of diet-induced adipose tissue inflammation." (PMID 38685031, 2024). "Notably, blockade of NLRP3 inflammasome activation could exert beneficial effects in different brain injuries." (PMID 36875102, 2023). "In several other studies, MCC950 was found to efficiently repress the NLRP3 inflammasome induced by traumatic brain injury and decrease the neurological severity score in mice model of unilateral cortical impact, controlled cortical injury impact and isofluorane-induced traumatic brain injuries." (PMID 31892810, 2019). "In a mice model of repetitive mild traumatic brain injury (TBI), saffron extract was proved to attenuate the NOD-like receptors family pyrin domain-containing 3 (NLRP3) inflammasome signaling activation via the enhanced expression of SIRT1 in neuronal cells." (PMID 40806702, 2025). "The calcium-sensing receptor (CaSR) plays a key role in activating NLRP3-mediated signaling cascades (e.g., NOD-like receptor signaling pathway) related to the occurrence of cardiovascular diseases and ischemic brain injury under hypoxic conditions." (PMID 36077479, 2022). "Similarly, in repetitive traumatic brain injury, SCH79797 inhibits neuronal ferroptosis and reduces NLR family pyrin domain containing 3 (NLRP3) inflammasome activation by promoting PPAR-γ/Nrf2-mediated antioxidant responses." (PMID 40093329, 2025). "The presence and the activation time of the NLRP3 inflammasome is important for maintaining the integrity of the blood–brain barrier (BBB) and the severity of the neurological damage that occurs after a brain trauma." (PMID 35893807, 2022). "Notably, in models of ischemic brain injury and neuralgia, DEX acts on oxidative stress processes to reduce the number of inflammatory microglia and NLRP3 inflammasome formation." (PMID 36204225, 2022). "We have determined that the NLRP3 inflammasome contributes to the SE-induced inflammatory response; however, the molecular basis of NLRP3 inflammasome activation in SE-induced brain injury has not been established." (PMID 25516224, 2014).
brain injury (continued). "Thus, therapeutic targeting of NLRP3 inflammasome may provide a novel and efficacious treatment for TBI, as well as other acute and chronic brain injuries involving the activation of the NLRP3 inflammasome." (PMID 28785377, 2017). "This exaggerated inflammatory response is detrimental because the absence of NLRP3 in knockout mice and the selective inhibition with MCC950 before brain trauma resulted in increased BBB permeability, leading to total BBB loss and an exacerbation of the neurological damage." (PMID 35893807, 2022).
cardiomyopathy (53 papers, 2017 to 2026). A disease of the heart muscle or myocardium proper. "Serum NLRP3 has been identified in patients with acute ischemic stroke, as well as in individuals with different cardiomyopathies, and has been associated to disease progression." (PMID 38816358, 2024). "NLRP3 inflammasome and Myd-88 activation have been implicated in several diseases, including cancer and cardiomyopathies." (PMID 38818214, 2024). "The key contributor to Ang II-induced cardiomyopathy is excessive ROS production, which not only causes oxidative stress but also triggers the NLRP3 inflammasome to induce myocardial injury." (PMID 36978920, 2023). "On the other hand, the upregulation of cardiomyocyte NLRP3 inflammasome has been implicated as causative in the inflammatory component of the cardiomyopathy resulting from pacing-induced arrhythmogenesis or pressure overload." (PMID 33101273, 2020). "Chagas cardiomyopathy, a parasite‐induced cardiomyopathy, is also associated with NLRP3 activation." (PMID 32508013, 2020). "Therefore, ROS plays a central role in the activation of oxidative stress and NLRP3-mediated inflammation, which might be associated with the occurrence of Ang II-induced cardiomyopathy." (PMID 36978920, 2023). "Another study demonstrates that inhibition of the NLRP3/IL-1β pathway mitigates cardiac atrophy and cardiomyopathy in septic mice." (PMID 39887250, 2025). "NLRP3 inflammasome inhibitors such as daggligin can alleviate cardiomyopathy in T2D by inhibiting NLRP3 inflammasome activation." (PMID 40438494, 2025). "Recent research emphasizes the significant roles of NLRP3 inflammasome and pyroptosis in obesity-related cardiomyopathy." (PMID 40430076, 2025). "For instance, further investigation is needed to confirm the effects of exercise on NLRP3 inflammasome pathways in cardiomyocytes, which can sense the chemical and mechanical alterations associated with DOX-induced cardiomyopathy." (PMID 39273638, 2024). "We report the first model of steatohepatitis-related cardiomyopathy characterized by activation of the NLRP3 inflammasome pathway." (PMID 35194060, 2022). "What this study has additionally provided is the novel finding that RLX appears to also modulate the P2X7R on HCMFs and, within the LV of ISO-induced mice with cardiomyopathy, to inhibit NLRP3 inflammasome activity." (PMID 35806076, 2022). "Nlrp3 gene knockout significantly attenuated Ang II-induced cardiomyopathy by ameliorating mitochondrial dysfunction and reducing cardiac inflammation, oxidative stress, and fibrosis." (PMID 33628380, 2021). "In conclusion, our study is the first to suggest that Nlrp3 inflammasome induced mitochondrial dysfunction is involved in Ang II-induced cardiomyopathy." (PMID 33628380, 2021). "Inhibition of downstream regulators of NLRP3 inflammasome also prevents the progression of cardiomyopathy." (PMID 33995071, 2021). "It has been proven that the knockout of NLRP3 or IL-1β receptor antagonists improved the mitochondrial structure of muscle fibers and ultimately restored cardiac function of cardiomyopathy via reducing the extracellular matrix." (PMID 33995071, 2021). "In conclusion, Nlrp3 inflammasome-induced mitochondrial dysfunction is involved in Ang II-induced cardiomyopathy." (PMID 33628380, 2021). "Numerous studies have confirmed that NLRP3 inflammasome is involved in the occurrence and development of myocardial I/R injury, cardiomyopathy, arrhythmia, and other diseases." (PMID 34432650, 2021). "A growing body of evidence indicates that cardiac non-immune cells, specifically myocytes and fibroblasts, can also assemble and activate the NLRP3 inflammasome during the development of various cardiomyopathies." (PMID 33101273, 2020). "The NLRP3/Caspase 1/IL-1 pathway is a key mediator of cardiomyopathy, doxorubicin-induced cardiotoxicity, and vascular diseases." (PMID 33086484, 2020).